KPNA2 (karyopherin subunit alpha 2)
Diseases named in the same sentence as KPNA2 in open-access papers (continued):
Sharing a sentence is not in itself a finding about the gene and the disease.
cancer (continued). "KPNA2 is an adaptor protein that mediates the nuclear import of various proteins associated with cancer proliferation." (PMID 28178675, 2017). "Karyopherin subunit alpha-2 (KPNA2) is overexpressed in various human cancers and is associated with cancer invasiveness and poor prognosis in patient." (PMID 27009856, 2016). "Accumulating evidence indicates that KPNA2 upregulation is significantly associated with poor prognosis in various human cancers." (PMID 26052702, 2015). "Karyopherin α2 (KPNA2), a protein implicated in the conventional pathway of nuclear protein transportation, has been observed in many instances of cancer, including HCC, Nevertheless, the exact molecular mechanisms responsible for the function of KPNA2 are still not fully understood." (PMID 38238845, 2024). "KPNA2 is involved in the nucleoplasm shuttle process of various oncoproteins, and highly expressed KPNA2 is linked to poor prognosis in patients with some kinds of cancer." (PMID 35915607, 2022). "KPNA2 encodes karyopherin α2 (importin α1), which is involved in nucleocytoplasmic protein transport and promotes proliferation, migration, and invasion in various types of cancer." (PMID 35884546, 2022). "For example, among the top eight high-significance genes (q-value < 0.005), dysregulation of KPNA2 (Karyopherin α2/Importin α) (q = 0.0009) has long been known to cause mitotic defects, and KPNA2 is reported as overexpressed in various cancers with poor prognosis." (PMID 34070461, 2021). "KPNA2 is involved in the nucleocytoplasmic transport pathway of multiple tumor-associated proteins, and is overexpressed in various cancers thereby being suggested as a prospect in the diagnosis and treatment of cancer." (PMID 34112092, 2021). "KPNA2 has been linked to cancer in many studies, including HCC." (PMID 34049287, 2021). "Because of the tight association between high levels of KPNA2 expression in cancer cells and resistance to anticancer therapy, we hypothesized that radiation-induced KPNA2 expression attenuates the efficacy of IR." (PMID 31212646, 2019). "Moreover, KPNA2 overexpression was significantly associated with cancer-specific and relapse-free survival (P = 0.02 and P = 0.0001, respectively)." (PMID 28178675, 2017). "KPNA2 may participate in carcinogenesis through regulating the subcellular translocation of cancer-associated cargo proteins." (PMID 27974678, 2017). "KPNA2 may affect oncogenesis by mediating the subcellular localization of cancer-associated cargo proteins." (PMID 25956057, 2015). "A reasonable way by which KPNA2 could affect carcinogenesis is through the translocation of cancer-associated cargo proteins." (PMID 26626145, 2015). "It raised the hypothesis that KPNA2 might affect cancer cells through the translocation of cancer-associated transcriptional factors." (PMID 25060425, 2014). "Furthermore, using iRIP-seq, we discovered that cancer-associated mRNAs can bind to KPNA2." (PMID 39060340, 2024). "Therefore, it is possible that high KPNA2 expression, observed during RT, causes poor responsiveness to cancer treatment; in these instances, alternative therapeutic options might be more advantageous than RT." (PMID 31212646, 2019). "However, the association between KPNA2 expression and prognosis in cancer remains controversial." (PMID 27974678, 2017). "Karyopherin α2 (KPNA2) is commonly upregulated across multiple cancer types and serves a crucial function in nuclear transport." (PMID 40918463, 2025). "In this study, we identified 76 target genes regulated by miR‐20a‐5p in BC, including KPNA2, which has been reported to function as an oncogene in various cancers." (PMID 40830912, 2025). "As a potential cancer biomarker, KPNA2 promotes tumorigenesis by affecting cell differentiation, proliferation and apoptosis." (PMID 40830912, 2025). "Previous work in our lab has demonstrated that inhibiting the cancer-promoting effects of S100A2 in tumors by blocking its interaction with KPNA2 can be effective." (PMID 40011447, 2025).
cancer (continued). "Accordingly, the abnormally high levels of KPNA2 during tumorigenesis and its potential role as a biomarker identify this protein as a potential target for cancer treatment." (PMID 41413918, 2025). "KPNA2 was found to be a potential oncogene in different malignant tumours, as demonstrated in our previous study." (PMID 40830912, 2025). "Elevated KPNA2 levels in exosomes across various cancers, including lung and esophageal cancers, underscore its potential as a circulating marker, but its precise role in BCa remains uncertain." (PMID 39956902, 2025). "KNPA2 inhibitor was developing but the complexity of cancer biology and the need for more comprehensive studies on the efficacy and safety of KPNA2-targeted therapies contribute to this limited clinical use." (PMID 40002266, 2025). "Our findings revealed that KPNA2 is upregulated during cancer development and that inhibiting its expression effectively reduced the proliferation of cancer cells." (PMID 41413918, 2025). "Forty-five patients with GC exhibited increased KPNA2 expression in cancer tissues (p < 0.0001), and 40 (63.5%) patients with GC exhibited KPNA2 mRNA levels that were at least twofold higher than those in the corresponding adjacent tissues." (PMID 39060340, 2024). "In this study, according to the GEPIA database, KPNA2 expression was increased in cancers of the digestive system." (PMID 39060340, 2024). "Genes related to cancer stem cells and tumorigenesis, such as KPNA2, ECT2, ERCC6L and TUBB4B, and the cell-cycle regulators DLGAP5, KIF2C and BUB3 were also significantly upregulated in the CSPG+ group, and clustered well within the same area." (PMID 38251863, 2024). "Dysfunctions in nucleocytoplasmic transport are commonly observed in malignant tumours, and KPNA2 is highly expressed in a variety of malignant tumours." (PMID 37423952, 2023). "In summary, we have demonstrated for the first time that ISG15 maintains cancer stem cell-like characteristics by inhibiting KPNA2 degradation through ISGylation in ATC." (PMID 37501099, 2023). "Taken together, these data demonstrated that KPNA2 mediated cancer stem-like characteristics of ATC reinforced by ISG15 and ISGylation." (PMID 37501099, 2023). "Due to the observation that KPNA2 mediated the modulation of ISGylation to cancer stem cell-like characteristics, the specific mechanisms by which the ISGylation of KPNA2 impacted upon itself aroused our great interest." (PMID 37501099, 2023). "For delineating the mechanism of ISG15 and ISGylation in modulate cancer stem cell-like characteristics, the physical interaction analysis was conducted to screen a range of potential substrates, including Karyopherin α2 (KPNA2)." (PMID 37501099, 2023). "Mechanistically, ISG15 mediated the ISGylation of KPNA2 and impeded its ubiquitination to promote stability, further maintaining cancer stem cell-like characteristics." (PMID 37501099, 2023). "The effect and mechanism of ISG15 and KPNA2 on cancer stem cell-like characteristics of ATC cells were determined by molecular biology experiments." (PMID 37501099, 2023). "The expression of IRF1 in NSCLC tissue was generally lower than that in normal lung tissue, which is cancer-suppressive by regulating KPNA2." (PMID 36245844, 2022). "Based on the findings, we postulated that during cancer cell differentiation, KPNA2 activates various co‐expressed genes that affect the differentiation of TSCC." (PMID 35860570, 2022). "Here, we demonstrated the cancer-promoting effects of KPNA2 in CAFs, suggesting that KPNA2 is closely involved in the interaction between CAFs and cancer cells via paracrine or autocrine pathways." (PMID 35884546, 2022). "As a validation step, patterns of KPNA2 expression were studied across 39,619 cancer samples in COSMIC." (PMID 35948941, 2022). "To test the effects of UBE2T, TK1, CXCL12, and KPNA2 on cancer cell invasion, we knocked down these genes in murine CAFs via siRNAs." (PMID 35884546, 2022).
cancer (continued). "In all searches performed, KPNA2 was ranked in the top 7% of genes dysregulated in cancer across breast cancer subtypes located." (PMID 35948941, 2022). "Literature confirms the importance of the top-ranked genes as KPNA2, recently identified as involved in cancer progression in several studies, or KIF11." (PMID 36175974, 2022). "During the last decades, many studies have demonstrated that KPNA2 acts as a key oncogenic factor in multiple human cancers including breast cancer, melanoma, liver cancer, and lung cancer." (PMID 33728352, 2021). "We discovered that invasion and migration in both cancer cells were inhibited after silencing KPNA2." (PMID 34469024, 2021). "Co-expressed genes with KPNA2 were identified by using LinkedOmics and made pairwise correlation by Cancer Regulome tools." (PMID 33821218, 2021). "Karyopherin alpha 2 (KPNA2), a member of the nuclear transporter family, is elevated in multiple human cancers and accelerates carcinogenesis." (PMID 33728352, 2021). "KPNA2 mRNA expression in six major cancers was investigated in Oncomine, the human protein atlas, and GEPIA databases." (PMID 33821218, 2021). "KPNA2 is a member of the karyopherin family and was reported to be upregulated in many cancer types." (PMID 32512858, 2020). "Numerous reports have described that karyopherin alpha 2 (KPNA2) is highly expressed in cancers of different kinds." (PMID 31179341, 2019). "Our findings provide new insights and suggest that knockdown of KPNA2 effectively improves the therapeutic effects of RT in patients with radioresistant cancer cells." (PMID 31212646, 2019). "The biological functions of KPNA2 have been involved in promoting cancer cell proliferation, colony formation, migration and invasion and in suppressing apoptosis." (PMID 31046781, 2019). "Cell cycle phase arrest upon silencing of KPNA2 has been shown before in human cancers outside the CNS." (PMID 30323892, 2018). "In spite of the crucial roles were disclosed, the mechanisms of KPNA2 in cancers, especially on cancerous metabolism still remains to be elucidated." (PMID 30115078, 2018). "Overexpression of KPNA2 has been commonly observed in many kinds of cancers, even in precancerous lesions, indicating that KPNA2 is a crucial element for cancer occurrence, development and prognosis." (PMID 30115078, 2018). "In the future, it will be necessary and valuable to explore the therapeutic potential of targeting KPNA2 for cancer treatment." (PMID 28422734, 2017). "On the other hand, knockdown of KPNA2 was shown to inhibit proliferation of cancer cells derived from lung, liver and prostate cancer." (PMID 27974678, 2017). "KPNA2 in cancer cells delivers numerous cargo proteins via nuclear localization signals to the nucleus including the DNA repair-associated MRN complex and proliferation-related protein c-Myc/E2F." (PMID 28178675, 2017). "These included Eno1, LDHB, NPM1, PKM2 and KPNA2, which are commonly overexpressed in NSCLC, are associated with poor prognosis, and are therefore potentially relevant targets for cancer immunotherapy." (PMID 29258618, 2017). "Our previous studies identified that high KPNA2 expression was correlated with poor prognosis and cancer progression in esophageal squamous cell carcinoma, gastric carcinoma, and colorectal carcinoma." (PMID 28178675, 2017). "Two of the lncRNAs, LOC146880 and ENST00000439577, were positively correlated with expression of two cancer-related genes, KPNA2 and RCC2, respectively." (PMID 27849024, 2016). "KPNA2 belonges to the karyopherin α family, which has been reported as a key nucleocytoplasmic transport protein in the translocation of several cancer-related proteins." (PMID 27849024, 2016). "KPNA2 has been identified and validated as a potential biomarker for many cancers, such as non-small cell lung cancer, breast cancer, ovarian cancer, and prostate cancer." (PMID 25956057, 2015).
cancer (continued). "Although KPNA2 plays an important role in cancers, limited information is available regarding factors that control its expression." (PMID 26204489, 2015). "KPNA2 is expressed more in various cancers than in normal tissues, and high expression of KPNA2 has been confirmed as a predictor of poor prognosis in different cancers." (PMID 26626145, 2015). "We also observed a significant correlation between KPNA2 and presence of Ki-67 (p = 0.002), suggesting a potential role for KPNA2 in the promotion of cancer cell proliferation and growth." (PMID 26626145, 2015). "Studies in cancer cells demonstrated that KPNA2 deregulation affects malignant transformation, thus it was considered a potentially relevant therapeutic target." (PMID 24748173, 2014). "Among the genes that drew our attention was KPNA2, which was increased in expression in 6 of 7 cancer types at the mRNA and the protein levels, with limited expression in normal epithelia." (PMID 23536776, 2013). "Noticeably, as a selective nuclear import protein whose immuno-regulatory function just begins to emerge, karyopherin alpha 2 (KPNA2) is uniformly up-regulated across cancer types." (PMID 23536776, 2013). "KPNA2, a gene overexpressed in many cancers, and MCM2 gene, an initiator of replication and necessary for entry into S phase of the cell cycle, were downregulated in the human cell cycle array." (PMID 24147107, 2013). "This approach has also led to the discovery and validation of KPNA2 as the single most consistently up-regulated protein in cancer." (PMID 23536776, 2013). "This work defines an inflammatory signature shared by seven epithelial cancer types and KPNA2 as a consistently up-regulated protein in cancer." (PMID 23536776, 2013). "KPNA2 is overexpressed in various cancers and correlates with poor prognosis, particularly in HCC where it is linked to immunological infiltration and may play a role in cell cycle regulation." (PMID 40612108, 2025). "KPNA2 (also known as Rch1 or hSRP1) plays a critical role in cell signal transduction and nucleocytoplasmic transport, and it has been shown to act as an oncogene involved in the occurrence and development of various cancers." (PMID 40830912, 2025). "Mechanisms promoting cancer by KPNA2 were examined using both in vivo and in vitro models." (PMID 39956902, 2025). "This methodology has the potential for identifying the critical regulatory genes involved in maintaining cell cycle coherent oscillation, such as CDC25C, CCNE2, KPNA2, etc., which may be the new targets in cancer." (PMID 38353329, 2024). "Additionally, the presence of functional clusters, such as the interactions among KPNA2, DHX37, and YARS1, indicates possible shared roles in critical cellular processes like RNA processing, which are often implicated in cancer progression." (PMID 39330100, 2024). "In this context, we examined the effects of KPNA2 on cancer stem-like characteristics of ATC cells." (PMID 37501099, 2023). "The regulation of the Myc target Kpna2 by Hira needs further exploration, and it would be interesting to investigate whether it occurs in other cancers, beyond HLRCC." (PMID 36269833, 2022). "Studies have shown that KPNA2 is a potential biomarker for a variety of cancers." (PMID 36522613, 2022). "Interestingly, fewer CAFs migrated toward KPNA2-knockdown cancer cells than toward control cancer cells in the coculture system, showing that KPNA2 bidirectionally regulates the interaction between cancer cells and CAFs." (PMID 35884546, 2022). "KPNA2 knockdown also suppressed cancer cell migration toward CAFs at the bottom wells." (PMID 35884546, 2022). "High KPNA2 was positively related to cancer invasiveness and poor prognosis, thus regarded KPNA2 as a potentially relevant therapeutic target for patients with different cancers." (PMID 36199790, 2022). "However, the proportion of KPNA2-positive staining with strong intensity remained high in all three grades of carcinoma tissues." (PMID 35991835, 2022).
cancer (continued). "KPNA2 protein was mainly expressed in nucleoplasm and cytosol in cancer cells." (PMID 33821218, 2021). "Additionally, we observed that KPNA2 appeared to be predominantly situated in the nucleus of cancer cells." (PMID 33728352, 2021). "Intriguingly, it has been reported that KPNA2 activates the AKT pathway in various cancers." (PMID 34903711, 2021). "Furthermore, overexpression of NPM1 also promoted the migration and invasion of cancer cells even though KPNA2 was repressed." (PMID 34469024, 2021). "Besides, Western blot was conducted to test KPNA2 and discovered that KPNA2 was greatly elevated in cancer cell lines in comparison with that in the normal epithelial cell line MCF 10A (p < 0.05)." (PMID 32355466, 2020). "KPNA2 has been reported to be involved in the pathogenesis of variety types of cancer." (PMID 31046781, 2019). "The family of karyopherins has been implicated in drug resistance in cancer; this effect of KPNA2 on chemosensitivity of GBM has not been investigated in the present study." (PMID 30323892, 2018). "Recently, KPNA2 has emerged as a potential biomarker in several cancers." (PMID 28178675, 2017). "The knockdown of KPNA2 could inhibit proliferation of several cancer cells including liver and lung and KPNA2 may be a useful prognostic biomarker to monitor cancer prognosis." (PMID 29100313, 2017). "KPNA2 could also enhance transcriptional activity of c-Myc, activate Akt, and suppress FOXO3a in various cancer cells." (PMID 27974678, 2017). "Moreover, the KPNA2 suppression strategy induced apoptosis and conferred anti-proliferation activity in several cancer cells." (PMID 28178675, 2017). "KPNA2 overexpression has been reported in several malignant tumors." (PMID 28178675, 2017). "KPNA2 (karyopherin alpha 2) may participate in carcinogenesis by regulating the translocation of some cargo proteins which are involved in cancer." (PMID 29100313, 2017). "Little is known regarding the transcriptional regulation of KPNA2 in cancer cells." (PMID 27009856, 2016). "To examine the essential role of KPNA2 protein complexes in cancer progression, we previously applied a quantitative proteomic strategy combined with immunoprecipitation to investigate the differential KPNA2 protein complexes in NSCLC cell lines with different invasiveness potential." (PMID 27009856, 2016). "It is reasonable to suggest that KPNA2 overexpression in cancer cells may perturb a variety of processes through the altered shuttling of its nuclear cargo proteins, thereby supporting carcinogenesis." (PMID 27009856, 2016). "Moreover, aberrant KPNA2 expression has been observed in several cancer types, suggesting a potential role in tumorigenesis." (PMID 27078844, 2016). "Although it is well-documented that KPNA2 is involved in tumorigenesis, the upstream signaling and/or transcriptional regulation of KPNA2 expression in cancer remain unclear." (PMID 27009856, 2016). "Phospho-mTOR/mTOR was also detected in the KPNA2-immunoprecipitated complex, which indicated that the induction of KPNA2 protein decay is a possible mechanism of rapamycin functioning in anti-cancer processing." (PMID 27009856, 2016). "In our study, knock down of KPNA2 decreased the proliferation, colony formation, and migration activity of colon cancer cells, giving further credit to the idea that KPNA2 affects the viability of cancer cells." (PMID 26626145, 2015). "Karyopherin alpha 2 (KPNA2) is a nuclear transport protein upregulated in many cancers." (PMID 26204489, 2015). "However, the mechanism on how KPNA2 contribute to tumorigenesis and the development of carcinomas remains poorly understood." (PMID 26204489, 2015). "Moreover, another member of the importins family, KPNA2, is uniformly up-regulated across cancer types and proposed as poor prognostic cancer marker." (PMID 24866763, 2014). "Finally, Karyopherin α 2 (KPNA2) has recently emerged as a potential biomarker in multiple human cancer forms." (PMID 24748173, 2014).